STAT1 (signal transducer and activator of transcription 1)
Diseases named in the same sentence as STAT1 in open-access papers (continued):
Sharing a sentence is not in itself a finding about the gene and the disease.
breast cancer (continued). "To unravel the mechanism that leads to senescence and apoptosis in breast cancer, we studied the activation of Stat1." (PMID 29796172, 2018). "The specific inhibitor of STAT1, fludarabine, was used to further check the mechanism of miR-29c function in breast cancer cells." (PMID 29796115, 2018). "In conclusion, our results suggest that high mRNA expression of all the individual STATs, except STAT1 and STAT2, are significantly associated with favorable OS in breast cancer patients, especially for the high pathological grade." (PMID 29326301, 2018). "As modulation of ERα levels is one feasible approach to target oestrogen signalling and cell proliferation, STAT1 is a potential drug target for ERα ‐positive breast cancers." (PMID 30334368, 2018). "The present study identified the involvement of STAT1 in facilitating ERα transcription in breast cancer cells." (PMID 30334368, 2018). "In tumor microenvironment, tumor-induced stromal STAT1 increased the progression of breast cancer via deregulating tissue homeostasis." (PMID 29796115, 2018). "We firstly reported that miR-29c plays a significant role in suppressing the progression of breast cancers by targeting the TIMP3/STAT1/FOXO1 pathway." (PMID 29796115, 2018). "We firstly illustrated that miR-29c exerted its regulatory function in breast cancers by activating the TIMP3/STAT1/FOXO1 pathway." (PMID 29796115, 2018). "Within the IFN genes, GBP1, CXCL10, IRF1, and STAT1 were described previously to be part of a tumor relapse-free signature in breast cancer patients." (PMID 30486871, 2018). "Herein we show that the ShcA pathway simultaneously activates STAT3 immunosuppressive signals and impairs STAT1-driven immune surveillance in breast cancer cells." (PMID 28276425, 2017). "Mammary tumors in the 129/SvEv mouse strain with knockout (KO) of Stat1 (129S6/SvEvTac-Stat1tm1Rds; 129:Stat1−/− or Stat1-null) are unique among genetically modified mouse (GMM) models of human breast cancer." (PMID 28865492, 2017). "In contrast to the expansile margins found in most mouse mammary tumors, Stat1-null tumors are characterized by local invasion into the surrounding tissues." (PMID 28865492, 2017). "Further, Stat1-null females exhibit a prolonged tumor latency that models the majority of human breast cancers that are age-related." (PMID 28865492, 2017). "STAT1 was found to be frequently down-regulated in neoplastic cells, as compared to their adjacent benign tissues in breast cancer, colorectal cancer and liver cancer." (PMID 28431406, 2017). "The levels of ACTA2 and STAT1 were increased in HER2-overexpressing breast cancer cells and tumors from HER2-positive breast cancer patients." (PMID 28881584, 2017). "By analyzing the public dataset, we found that ACTA2 and STAT1 expression were relatively higher in HER2-positive than in HER2-negative breast cancers." (PMID 28881584, 2017). "Conflicting literature supports both pro- and anti-tumorigenic roles for STAT1 in breast cancer development." (PMID 28276425, 2017). "They further suggest that increased STAT1 signalling in MT/Shc313F/313F mammary tumours is insufficient to promote immune suppression, because they retain elevated STAT3 activity." (PMID 28276425, 2017). "ACTA2 and STAT1 expression was also higher in HER2-positive breast cancers than in HER2-negative cancers." (PMID 28881584, 2017). "STAT1 is frequently down-regulated in various types of human cancer, such as breast cancer, head and neck cancer, multiple myeloma and leukemia, and these findings are in line with the postulated role of STAT1 as a tumor suppressor." (PMID 28431406, 2017). "In contrast, STAT1 deficiency in STAT3Low mammary tumours (MT/Shc2F/2F) significantly accelerated their growth, suggesting that STAT1 selectively confers an immune surveillance response in mammary tumours with low STAT3 activity." (PMID 28276425, 2017).
breast cancer (continued). "Levels of ACTA2, STAT1, and HER2 were increased and relapse free survival was decreased in high-risk breast cancer patients." (PMID 28881584, 2017). "In conclusion, we demonstrated that dimerization of EGFR and HER2 induced ACTA2 expression through a JAK2/STAT1-dependent signaling pathway that triggers breast cancer cell motility." (PMID 28881584, 2017). "HER2 overexpression resulted in enhancement of ACTA2 and STAT1 expression in EGFR-positive breast cancer cells." (PMID 28881584, 2017). "High-risk breast cancer patients with highly expressed ACTA2, STAT1, and HER2 had significantly decreased relapse-free survival." (PMID 28881584, 2017). "Aberrant ACTA2 and STAT1 expression correlated with worse clinical outcomes of breast cancer patients." (PMID 28881584, 2017). "We found that expressions of alpha-smooth muscle actin (ACTA2) and signal transducer and activator of transcription 1 (STAT1) significantly increased with transient or stable overexpression of HER2 in EGFR-positive breast cancer cells." (PMID 28881584, 2017). "Taken together, our results suggest that TA modulates EGF‐R/Jak2/STAT1/3 and P38/STAT1/p21Waf1/Cip1 pathways and induce G1‐arrest and intrinsic apoptosis in breast carcinomas." (PMID 27862996, 2017). "Stat1 gene-targeted knockout mice (129S6/SvEvTac-Stat1tm1Rds) develop estrogen receptor-positive (ER+), luminal-type mammary carcinomas at an advanced age." (PMID 28865492, 2017). "This study adds a level of complexity by providing the rationale for considering genotoxic-induced activation of the STING/IFN/STAT1 pathway in breast cancer cells as a cell-intrinsic mechanism of escape to treatment." (PMID 27791205, 2016). "The role of STAT1 in breast cancer is not fully understood, with studies suggesting both tumor suppressing, and tumor promoting activities." (PMID 26894864, 2016). "Five studies have examined the prognostic value of STAT1 in breast cancer, using either total STAT1 or phosphorylated STAT1 (ph-STAT1)." (PMID 27769057, 2016). "Taken together, these data indicate that the type I IFNs/IFNAR1/STAT1 pathway plays a critical role in mediating ISG upregulation in breast cancer cells in response to genotoxic treatment." (PMID 27791205, 2016). "Using qPCR analysis, we detected an increased expression of the majority of the IFN/STAT1 signature (21 genes) that we previously identified as representative of the drug-induced ISGs in breast cancer PDXs." (PMID 27791205, 2016). "Pro-inflammatory cytokines TNF-α and IFN-γ also enhanced the expression of MUC1 in breast cancer cells through NF-κB and signal transducer and activator of transcription 1 (STAT1) activation, respectively." (PMID 27754373, 2016). "Together, these data strongly suggest that breast cancer cells treated with mafosfamide secrete functional cytokines able to trigger paracrine STAT1 signaling, among which type I IFNs appear to be relevant candidates." (PMID 27791205, 2016). "SSM2 and SSM3 breast cancer cell lines have been derived from primary tumors in STAT1−/− mice and express ERα and PR." (PMID 27391074, 2016). "By using two ERα+ cell lines derived from spontaneous mammary carcinomas in STAT1−/− mice (SSM2, SSM3), we establish that the bone microenvironment offers growth advantage over primary site or lung in the absence of ovarian hormones." (PMID 27391074, 2016). "The 129S6/SvEvTac-Stat1tm1Rds homozygous female mice used herein (129:Stat1-null hereafter) spontaneously develop distinctive estrogen receptor (ER) positive mammary tumors that mimic human luminal intrinsic subtypes of breast cancer." (PMID 26075897, 2015). "Since 129:Stat1-null mice model neoplastic development of ER-positive mammary tumors later in human life, the model warrants further attention." (PMID 26075897, 2015). "The 129:Stat1-null females develop mammary tumors having a unique ER+, progesterone receptor (PR)+ histological signature distinct from other models." (PMID 26075897, 2015).
breast cancer (continued). "Female 129:Stat1-null mice (129S6/SvEvTac-Stat1tm1Rds homozygous) uniquely develop estrogen-receptor (ER)-positive mammary tumors." (PMID 26075897, 2015). "In a study of 47 premenopausal and 118 postmenopausal breast cancer patients, tumor expression of phosphorylated STAT1(Tyr 701) was reported to correlate with poor survival in premenopausal women, but not in postmenopausal women." (PMID 24728078, 2014). "STAT1 has been shown to have tumor-suppressive functions against spontaneous and induced solid cancers, including breast cancer." (PMID 24489749, 2014). "The most striking result of our study is the opposing impact of STAT1 pY701 levels versus STAT1 expression and transcription of STAT1 target genes on prognosis in mammary cancer." (PMID 24725474, 2014). "STAT1 protein levels in tumor epithelium and stroma were separately assessed by immunohistochemical staining of primary breast cancer tissue derived from 83 patients." (PMID 24725474, 2014). "Decreased or loss of STAT1 expression has been observed in many cancer types such as breast cancer, melanoma and leukemia; transfection of STAT1 or STAT1C into cancer cells can arrest their growth by inducing apoptosis and cell-cycle arrest." (PMID 25355139, 2014). "The proof of principle for the importance of STAT1 in impeding the development of tumors came from experiments with MMTV-neu tumor STAT1 null mice, which develop mammary tumors with shorter latency as compared to STAT1-proficient controls." (PMID 24725474, 2014). "One possible mechanism for the higher constitutive expression of PD-L1 in certain basal breast cancer cell lines is higher levels of STAT1 and lower levels of IRF2BP2 expression." (PMID 24551119, 2014). "The coordinate upregulation of STAT1 target genes and markers for immune infiltration indicates a close interplay between activity of the immune system and induction of STAT1 target genes in mammary tumors." (PMID 24725474, 2014). "Recent studies have revealed that the expression of STAT1 is frequently lost in various types of human cancer such as breast cancer, head and neck cancer, multiple myeloma and leukemia." (PMID 25355139, 2014). "Surprisingly, however, in that report the authors found that breast cancer patients with high expression of STAT1 had worse prognosis." (PMID 24818101, 2014). "Genome-wide expression analysis revealed that fibroblasts induce the expression of STAT1 and interferon-responsive genes also in breast cancer cells, suggesting that interaction of breast cancer cells and fibroblasts induces an interferon response." (PMID 24818101, 2014). "MCF7, an estrogen receptor-positive breast cancer cell line, served as the positive control for STAT1." (PMID 25355139, 2014). "The CCND1, CCNB1, and STAT1 genes neighboring BRCA1 have also been reported to have important roles in breast cancer recurrence." (PMID 24497942, 2014). "Their functions in endocrine-sensitive and resistant breast cancer are still poorly defined and the published literature indicates complex roles, particularly for STAT1 and STAT3." (PMID 24728078, 2014). "A microarray study evaluated STAT1 expression in a large series of breast cancers and expression was observed in 21% of 923 breast cancers with its presence being associated with poor survival." (PMID 24728078, 2014). "Stat1 and Stat3 are expressed in both the tumor cell and stromal cell compartments of breast cancers." (PMID 23520493, 2013). "Recent microarray studies have shown high expression levels of Stat1 and Stat3 in primary breast cancers, with several studies grouping Stat1 within the top one percent of most highly expressed genes." (PMID 23520493, 2013). "In breast cancer patients, an interferon-related gene signature, which included Stat1 and interferon-γ-induced genes, is predictive of poor response to chemotherapy or radiation." (PMID 23520493, 2013).
breast cancer (continued). "Co-immunofluorescence with a macrophage marker showed that Stat1 was expressed in tumor cells, as was reported in breast cancers." (PMID 23520493, 2013). "Human breast cancer samples have been known to contain high levels of p-Stats, in particular p-Stat1, p-Stat3, and p-Stat5." (PMID 23520493, 2013). "HER2- and HER2+ breast cancers displayed similar percentages of STAT1+ cells and levels of STAT1 intensity in the stromal and neoplastic compartments." (PMID 22264274, 2012). "Forty-five percent (37/83) of human ERα+ and 22% (17/78) of ERα- breast cancers display undetectable or low levels of STAT1 expression in neoplastic cells." (PMID 22264274, 2012). "Biologically, STAT1-/- mammary tumor cells depend on ovarian hormones for both the initiation and the maintenance of tumor growth." (PMID 22264274, 2012). "Our findings demonstrate that STAT1 suppresses mammary tumor formation and its expression is frequently lost during breast cancer progression." (PMID 22264274, 2012). "In agreement with our previous report, we observed mammary tumor development in a larger cohort of STAT1-/- × RAG2-/- female mice in similar disease incidences." (PMID 22264274, 2012). "The resulting P value is 0.99998, which indicates that the STAT1-/- mammary tumors are highly likely to be in the same cluster with the human luminal breast cancer datasets." (PMID 22264274, 2012). "It is conceivable that STAT1 promoter methylation is likewise in action during breast cancer progression." (PMID 22264274, 2012). "At present, it is not possible to conclude that these hormones are required for the tumorigenesis of the STAT1-/- mammary glands since nulliparous STAT1-/- mice also develop mammary tumors." (PMID 22264274, 2012). "In all of the 11 STAT1-low breast cancer cases in which adjacent normal breast tissues were available, normal breast tissues had significantly more STAT1+ epithelial cells and exhibited stronger staining intensity than matched tumor tissues." (PMID 22264274, 2012). "For these reasons, the STAT1-/- mammary tumor is an exceptional model for human ERα+ PR+ luminal breast cancers." (PMID 22264274, 2012). "Together, the STAT1-/- ERα+ mammary tumors display high molecular homogeneity and a striking similarity to human luminal breast cancers." (PMID 22264274, 2012). "It is then noteworthy that STAT1 expression is also diminished in the neoplastic cells of 22% of the human HER2+ breast cancer cases that we examined in this study." (PMID 22264274, 2012). "These murine STAT1-/- mammary tumors closely recapitulate the progression and biology of human ERα+ luminal breast cancers." (PMID 22264274, 2012). "STAT1-/- mice developed mammary tumors only, whereas STAT1-/- × RAG2-/- mice developed mammary and intestinal tumors." (PMID 22264274, 2012). "Specifically, we find, much to our surprise, that STAT1-/- female mice spontaneously develop mammary gland adenocarcinomas that show remarkable similarities to human ERα+ luminal breast cancers." (PMID 22264274, 2012). "Our results thus validate the physiological relevance of our novel mouse ERα+/PR+ STAT1-/- mammary tumors for potential translatability to human breast cancer research." (PMID 22264274, 2012). "The hormone receptor status of the STAT1-/- mammary tumors also shows a remarkable parallel to human ERα+/PR+ breast cancers." (PMID 22264274, 2012). "The STAT1-/- mammary tumors and human luminal breast cancers cluster together 62% out of 1,000 re-samplings with an IQR of 0.57 to 0.67 (range = 0.32 to 0.78)." (PMID 22264274, 2012). "To extend these findings, we compared the gene expression patterns of the datasets (primary data generously provided by Dr. Charles M Perou, University of North Carolina at Chapel Hill) with those of five primary STAT1-/- ERα+ mammary tumors." (PMID 22264274, 2012). "This is underscored by the potent anti-tumor action of ovarian ablation therapy on the STAT1-/- mammary tumors." (PMID 22264274, 2012).
breast cancer (continued). "Most importantly, STAT1-/- mammary tumors express elevated levels of ERα, PR, GATA3, AREG, XBP1, and FOXA1, all of which are regulated by the transcriptional control of ERα." (PMID 22264274, 2012). "Together, these results indicate that the STAT1-/- mammary tumor cells exhibit a marker phenotype that is characteristic of luminal epithelial cells." (PMID 22264274, 2012). "STAT1-/- ERα+ mammary tumors also showed elevated transcription of genes characteristic of luminal breast cancers (for example, keratin 8, keratin 18, XBP1, GATA3, MYB, AREG, and FOXA1)." (PMID 22264274, 2012). "We applied sigClust to five STAT1-/- primary tumor samples and 63 human luminal breast cancer samples by using the 96-gene intrinsic gene list." (PMID 22264274, 2012). "Total RNAs were isolated from normal mammary glands of primary STAT1-/- mammary tumors by using Trizol in accordance with the procedure of the manufacturer (Invitrogen Corporation)." (PMID 22264274, 2012). "In contrast, STAT1-/- mammary tumors exhibit well-defined tumor progression kinetics and a set of highly reproducible and homogeneous histopathological, biological, and molecular characteristics that closely resemble human luminal breast cancers." (PMID 22264274, 2012). "Hierarchical clustering analysis revealed that the five primary STAT1-/- ERα+ mammary tumors not only resembled one another but also closely resembled human luminal breast cancers." (PMID 22264274, 2012). "Strikingly, multiparous STAT1-/- mice developed mammary tumors sooner and at a higher frequency than nulliparous STAT1-/- mice." (PMID 22264274, 2012). "STAT1 is of particular interest in mammary cancer as it is known to possess an independent prognostic significance in human breast cancer: high activation of STAT1 has been reported to correlate with an overall longer and relapse-free survival." (PMID 22185785, 2011). "This conclusion suggests that STAT1 has an autonomous role in neu/ERBB2-induced mammary tumor formation." (PMID 22185785, 2011). "The fact that only 2/13 of the mammary cancers expressed ERBB2/neu/HER2 indicates that STAT1's tumor-suppressing effect is not limited to ERBB2/neu/HER2-induced tumorigenesis." (PMID 22185785, 2011). "Stat1+/+ as well as Stat1−/− mammary tumors occurred with an increased incidence in a Stat1−/− environment compared to in Stat1+/+ surroundings (15% versus 11% for Stat1+/+ tumors; 54% versus 30% for Stat1−/− tumors)." (PMID 22185785, 2011). "Our findings are in line with recent reports on the role of STAT1 in the context of ERBB2/neu/HER2 induced mammary cancer development." (PMID 22185785, 2011). "In the control group, only 10% had mammary tumors and disease onset was significantly later (Stat1−/−: 394.5 days ± 13.52 and Stat1+/+: 479.3 days ± 11.46; **P = 0.0089; values represent mean ± SEM)." (PMID 22185785, 2011). "We consistently observed mosaic expression or down-regulation of STAT1 protein in wild-type mammary cancer evolving in the control group." (PMID 22185785, 2011). "To evaluate the role of STAT1 in the spontaneous development of mammary tumors we crossed Stat1−/− mice into the BALB/c genetic background." (PMID 22185785, 2011). "By transplanting Stat1−/− mammary glands into wild type recipient mice and vice versa we reveal that STAT1 contributes to the formation of mammary tumors through cell-intrinsic as well as immunological activities." (PMID 22185785, 2011). "We show that the transcription factor STAT1 has a tumor-suppressing function against the formation of parity-induced, spontaneous mammary tumors." (PMID 22185785, 2011). "The type II receptor complex activates OSM-specific signaling pathways via the JNK/SAPK and Stat1/Stat5 pathways, whereas both type I and type II complexes activate Stat3 and Erk as common signaling pathways in breast cancer cells." (PMID 19662090, 2009).